EGF (epidermal growth factor)
Diseases named in the same sentence as EGF in open-access papers (continued):
Sharing a sentence is not in itself a finding about the gene and the disease.
tumor (continued). "In this context, it has been shown that the activation of the proinflammatory NF-kB pathway has a tumor prosurvival effect, giving chemotherapy resistance to cancer cells in an Akt-independent pathway, but involving the epidermal growth factor (EGF) activating signaling." (PMID 30627539, 2018). "EGF signalling deregulation often correlates with tumour overgrowth and metastasis." (PMID 29854765, 2018). "Furthermore H3tre11 is a specific substrate for tumor specific pyruvate kinase M2 (PKM2) in EGF mediated transcription initiation and H3K9 acetylation, thus leading to tumor cell proliferation." (PMID 29541423, 2018). "Their results suggest that even though EGF expression is low in cancer cell lines, it might be critical for maintaining tumor cell proliferation, and this might be also sufficient to confer resistance to cetuximab." (PMID 30308958, 2018). "Several studies have shown that soluble factors such as EGF and TGFβ serve as potent chemotactic factors in tumors and may promote migration of microglia towards the tumor as observed in the present study." (PMID 29861845, 2018). "Overgrown tumor cells are in a state of oxygen deficiency (hypoxia), which leads to an angiogenic switch for secretion of pro-angiogenic factors, including VEGF, FGF, PDGF, and EGF." (PMID 30618749, 2018). "However, tumor diameter increased by 53% (p = 0.0003) in EGF-treated mice and decreased by 26% (p = 0.03) in gefitinib-treated animals." (PMID 29904166, 2018). "Several growth factors, including epidermal growth factor, vascular endothelial growth factor, and transforming growth factor-α, also contribute to the creation of microenvironments supportive of angiogenesis and tumor proliferation." (PMID 30513928, 2018). "Over the last decades it has been extensively reported that tumor associated macrophages are able to promote tumor cell migration thought secretion of matrix-remodeling proteins, cytokines and chemokines (e.g. MMP-2, MMP-9, TNF-α, VEGF, TGF-β, EGF)." (PMID 29728948, 2018). "Mechanisms by which TAMs facilitate intravasation of tumor cells are mediated via molecular interactions that involve for example a paracrine loop in which epidermal growth factor (EGF), produced by TAMs, increases the invasiveness and migration of cancer cells expressing the EGF receptor (EGFR)." (PMID 29584702, 2018). "TAMs aid sphere formation and tumor growth, by secreting the epidermal growth factor (EGF)." (PMID 30274280, 2018). "For instance, EGF plays an important role in tumour proliferation and metastasis; PDGFβ induces liver fibrosis and accelerates tumour development; VEGFA is one of the major growth factors responsible for angiogenesis; and IGF2 enhances tumour cell proliferation." (PMID 29346427, 2018). "Looking over the results of transcriptome analysis we found that most of the tumor-promoting growth factors, such as epidermal growth factor (EGF), hepatocyte growth factor (HGF), nerve growth factor (NGF) or interleukin 6 (IL-6) were expressed at similar level in ASC.B6 and vASC." (PMID 30185144, 2018). "In addition, receptor ubiquitinylation – which marks the receptors that are to be targeted to endocytosis and degradation – occurred to a similar extent in tumor cells and in cultured cells treated with picomolar concentrations of epidermal growth factor." (PMID 29300164, 2018). "Accordingly, the inhibition of CSF-1 or EGF signaling in tumor-bearing mice undergoing intravital imaging experiments reduced metastasis by decreasing the number of macrophages and tumor cells able to leave the primary tumor." (PMID 30200242, 2018). "CSCs may form oncospheres in serum-free cultures supplemented with B27 and N2 supplements, as well as EGF and bFGF, making this technology widely used in the characterization of tumor cells with stem cell characteristics." (PMID 29422082, 2018).
tumor (continued). "Since PLD2 has been reported to promote the EGF receptor (EGFR) endocytosis through the activation of the Dynamin GTPase39, PLD2 might inhibit the EGF/EGFR circuit among tumor cells and stromal cells by limiting cell surface EGFR of stromal cells." (PMID 29674728, 2018). "We next examined whether the effect of EGF and OA was mediated through alteration of tumour cell aerobic glycolysis." (PMID 28067230, 2017). "In addition to links between PAD2 and EGF-mediated tumor cell migration, we also found that overexpression of PAD2 in FVB mice lead to mammary gland hyperbranching, thus supporting a role for PAD2 in mammary tumorigenesis." (PMID 28549415, 2017). "These dichotomous effects arise because TAMs, M2-type macrophages, produce tumor growth factors such as epidermal growth factor, angiogenic factors such as vascular endothelial growth factor, and metastasis promoting factors such as matrix metalloproteinase (Qian and Pollard, 2010)." (PMID 28900373, 2017). "In mouse models of breast cancer, macrophages contribute to tumor progression through a variety of mechanisms including IL-10 and arginase 1 (Arg1)-mediated immunosuppression, MMP 7/9 and CCL18-induced matrix remodeling, and EGF and TNFα-stimulated tumor cell migration and metastasis." (PMID 28881599, 2017). "The monospecific enediyne-energized fusion proteins EGF-LDP-AE and LDP-IGF-AE (at 0.4 mg/kg) demonstrated similar antitumor activity (67.6% and 72% tumor growth inhibition, respectively, p > 0.05) to the bispecific fusion protein EGF-IGF-LDP-AE when given at 0.2 mg/kg." (PMID 28460483, 2017). "Increased levels of EGF and TGF-β can cause activation of VEGF and subsequent tumor angiogenesis." (PMID 29276515, 2017). "We previously reported that EGF inhibits tumor cell growth, likely by triggering apoptosis." (PMID 27935858, 2017). "However, EGF mediated the alternation of claudin protein expression are a great difference and depend on the different cell type and tumor as previous described." (PMID 28160565, 2017). "Binding of EGF also induces the endocytosis of E-catherin, a cell adhesion transmembrane protein, resulting in disruption of cell-cell contacts and β-catenin-Tcf/Lef transactivation which contributes to tumor cell invasion." (PMID 28629170, 2017). "EGF treatment partially inhibited proliferation and induced cell death in tumor tissues." (PMID 27935858, 2017). "In attempt to dissect whether CCL3 influences the tumour milieu, we evaluated the expression of molecules involved in tumour proliferation (EGF, FGF, TGF-β and TNF-α) and angiogenesis (TGF-β1, VEGFa and VEGFb)." (PMID 28881626, 2017). "There are various ways to achieve this, for example, covering the viral surface with polymer to “cloak” the existing receptor and addition of epidermal growth factor (EGF) to target the virus to tumor cells which tend to have upregulated EGF receptor (EGFR) expression." (PMID 28944214, 2017). "Whereas, EGF-injected tumor size was significantly decreased compare with control tumor size." (PMID 27935858, 2017). "MATN2 traps EGFR at the cell surface for enhanced activation by EGF, driving tumour progression." (PMID 28416796, 2017). "In contrast, EGF elicited a very distinct tumour cell behaviour, both in DAOY and UW228 cells." (PMID 28706234, 2017). "Our report strongly suggests that Kaempferia parviflora contains active compounds which may directly or indirectly inhibit EGF-dependent signal transduction pathways and subsequently suppress tumor progression and induce cancer cell death." (PMID 28955234, 2017). "Our finding that PAD2 appears to function within the EGF signaling pathway to modulate DCIS tumor cell migration suggests that PAD2 and/or citrullination may have predictive power for identifying aggressive EGFR+ DCIS lesions." (PMID 28549415, 2017). "Macrophages in turn, produce EGF, which leads to tumor cell migration." (PMID 28471401, 2017).
tumor (continued). "Taken together, these results suggest that the EGF-induced nuclear targeting of PAD2 may lead to PAD2-mediated upregulation of genes involved in tumor cell migration." (PMID 28549415, 2017). "Therefore, on the one hand, the weak expression after HisDianthin‐EGF treatment can indicate that the tumor is now less aggressive after eradicating the part of tumor cells with high expression level." (PMID 28755527, 2017). "Another crucial growth factor, EGF, also plays a great role in the process of tumor development." (PMID 29050226, 2017). "As M2 macrophages secrete growth factors, such as Wnt ligands and EGF, this could contribute to tumor progression through a feed forward cross talk between the epithelium and the immune system." (PMID 28687085, 2017). "Besides the pro-angiogenic and immunosuppressive effects, TAMs can also facilitate tumor cell invasion and metastasis via secreting various proteolytic enzymes, cytokines and chemokines such as MMPs, cathepsins, EGF, and CCL18." (PMID 28848446, 2017). "Given that EGF signaling plays an important role in tumor cell migration, we tested whether there is a link between PAD2 and EGF." (PMID 28549415, 2017). "We also found that the PAD inhibitor, BB-Cl-Amidine, inhibits EGF-induced tumor cell migration." (PMID 28549415, 2017). "There was a 96.5% average reduction in the tumor volume for the group treated with the combination of HisDianthin‐EGF and SO1861 compared to the placebo (tumor volume 84.5 ± 51.9 mm3 for placebo and 3.0 ± 3.3 mm3 for combination) and four of five mice showed complete regression." (PMID 28755527, 2017). "We next treated the A549 tumour cells with EGF or OA and examined whether the effect of these reagents was mediated through alteration of tumour cell aerobic glycolysis." (PMID 28067230, 2017). "As is known, VEGF and EGF play a central role in the process of tumor angiogenesis." (PMID 29050226, 2017). "TAMs are known to promote invasion of tumor cells at the tumor periphery by supplying pro-migratory factors such as epidermal growth factor (EGF), by regulating the production of collagen to accelerate tumor motility, and by promoting extracellular matrix proteolytic remodeling." (PMID 28176853, 2017). "Moreover, as was the case in vitro, RAC1, p22phox, EGR1, and PTEN expression were higher in tumor tissues from EGF-treated mice compared to tumor tissues from PBS-treated control mice." (PMID 27935858, 2017). "In this report, we combine a similar strategy with the nanotechnology approach by coadministration of unlabelled targeting ligand instead of unlabelled NP, and study the effect of this coadministration strategy on the tumour and normal tissue uptake of 111In-EGF-Au-PEG NP." (PMID 29071190, 2017). "EGF treatment also markedly reduced cell proliferation rates, as indicated by Ki67 immunohistochemistry, in xenograft tumor tissue, indicating that EGF attenuated tumor growth in vivo as well as in vitro." (PMID 27935858, 2017). "However, either EGF-enhanced tumor cell invasion or EGF-induced transcription of MMP2 and Twist was compromised by MIIP depletion." (PMID 29038521, 2017). "To determine whether EGF treatment similarly inhibited tumors in vivo, we examined Ki67 expression to assess tumor cell proliferation." (PMID 27935858, 2017). "Moreover, this novel function of EGFR kinase is also observed in several EGF-stimulated tumor cell lines and normal skin fibroblasts." (PMID 29253018, 2017). "Proliferation was suppressed in the EGF-exposed area compared to control tumor tissues." (PMID 27935858, 2017). "By day 3 there was a significant difference in tumor dissemination when comparing the stimulated (715 ± 38.0 μm) and unstimulated conditions (556 ± 24.7 μm), demonstrated by a rightward distribution shift by (+) EGF cells along the x-axis." (PMID 27678304, 2016). "The expression of EGF/EGFR was correlated with tumor proliferation, invasion, and metastasis." (PMID 27788491, 2016).
tumor (continued). "Tumor cells from Mgat5-/- mice fail to undergo epithelial-to-mesenchymal transition and are insensitive to multiple cytokines, including epidermal growth factor (EGF), patelet-derived growth factor (PDGF) and transforming growth factor beta (TGF-ß)." (PMID 26760037, 2016). "The macrophages also promote the invasion of tumour cells by means of the supply of migratory factors, such as EGF, which through the regulation of the production of fibrillar collagen, accelerate cellular motility and induces proteolytic activity for the remodelling of the extracellular matrix." (PMID 26913068, 2016). "The EGF-evoked cancer cell response might have depended not only on the mutational status of cancer cells, but also on the interactions between EGF and other stimuli, which are likely to occur in the tumor microenvironment." (PMID 27655713, 2016). "Importantly, EGFL7, as a type of epidermal growth factor, is highly expressed in the blood vessels of a variety of tumor and tumor adjacent tissues." (PMID 27611944, 2016). "Tumor cells secrete a variety of tumor associated growth factors (TAF) like VEGF (vascular endothelial growth factor), TGF (transforming growth factor), EGF (epidermal growth factor), PDGF (platelet-derived growth factor), PAI, and TSP-1 to promote the process of angiogenesis." (PMID 27047544, 2016). "Importantly, inhibition of EGF-mediated PD-L1 stabilization enhances a therapeutic efficacy of PD-1 blockade to promote tumour-infiltrating cytotoxic T-cell immune response." (PMID 27572267, 2016). "To determine the role of p85α in the regulation of cell transformation, we first utilized EGF as a tumor promoter to establish an EGF-induced cell malignant transformation experimental system and consequently evaluated EGF-induced anchorage-independent growth abilities in p85α+/+ and p85α−/− cells." (PMID 26918608, 2016). "Interestingly, we found EGF accelerated tumour cell migration more greatly in the presence of MYCT1 than EV or MYCT1(ΔTM)." (PMID 26710964, 2016). "Furthermore, ex vivo distribution and gene expression of dendriplexes and h-R3/EGF/HSA-dendriplexes were determined in tumor-bearing BALB/c nude mice." (PMID 26883109, 2016). "Overall, our study supports the idea that targeting EGF/BMPs could be a valuable alternative to inhibit MMP-dependent tumor progression, at least in some types of cancer." (PMID 25897433, 2015). "Freshly isolated tumor cells were cultured in two different conditions: the first condition was chosen to enrich for GSCs (serum-free neural stem cell medium supplemented with EGF and bFGF), while the second condition was chosen to enrich the main/bulk tumor population (10% FBS in DMEM medium)." (PMID 25987130, 2015). "ADAM12 is selectively expressed in GBM tissues where it might be involved in supporting tumor cell proliferation that is mainly sustained by enhanced EGF signaling through EGFR." (PMID 26437223, 2015). "M2 macrophages can support tumor growth by secreting EGF, PDGF, FGF, VEGF, TGF-β, IL-4, and IL-13." (PMID 26694366, 2015). "We further studied PTX3 expression in various malignant tumor cells treated with EGF." (PMID 25797258, 2015). "In the tumour microenvironment, TAMs resemble M2-macrophages and induce the production of a large range of growth factors and proteolytic enzymes such as EGF, TGFβ1, VEGE and MMPs to stimulate ECM degradation, thus promoting tumour metastasis, resulting in poor cancer prognosis." (PMID 25692297, 2015). "Indeed, we found that the interaction between β4 integrin and FAK occurred in an EGF/Src-dependent manner, indicating the importance of this complex in the dialogue with microenvironmental cues and in the regulation of tumor progression." (PMID 26549523, 2015). "Inhibition of NRP-1 function may also result in modulation of signal transduction pathways triggered by growth factors other than VEGF-A, such as PDGF, FGF, EGF, and HGF, which are implicated in tumor progression and are capable of binding NRP-1." (PMID 26090340, 2015).
tumor (continued). "Importantly, tail-vein injection animal model revealed that depletion of PTX3 significantly blocked EGF-primed tumor cell metastatic seeding of the lungs." (PMID 25797258, 2015). "The present study identifies the proteolytic cleavage of extracellular TFPI-2 by trypsinogen 4 as a new pathway regulating the response of tumor endothelial cell to the factors VEGF-A,FGF-2 and EGF (which characterize the angiogenic milieu), and hence tumor angiogenesis." (PMID 26318044, 2015). "Moreover, the observed induction of creatine kinase in tumours of EGF transgenic mice creates a circuitry for cellular energy homeostasis in conditions of high metabolic demands." (PMID 25872475, 2015). "In exchange for pro-growth factors, GAMs provide the tumor with matrix metalloproteinases, which facilitate tumor growth and invasion, as well as tumor proliferation promoting factors, such as epidermal growth factor (EGF) and vascular endothelial growth factor (VEGF)." (PMID 26217588, 2015). "EGF contributed to tumor proliferation in EC cell lines along with EGFR expression in vitro." (PMID 26673416, 2015). "To further clarify whether the COX-2 induction is a general phenomenon of EGF-treated tumor cells, we examined several types of tumor cell lines." (PMID 25595899, 2015). "Furthermore, we investigated the serum proteome of EGF-tumour-bearing mice to obtain information on disease-regulated proteins and to search for novel biomarkers at different stages of disease." (PMID 25872475, 2015). "Likewise the tumour specific expression of the RAGE binding proteins lectin, galactoside-binding, soluble, 3 and CAPZA1 in tumours of EGF transgenic mice is highly suggestive for a sustained crosstalk between RAGE and EGFR." (PMID 25872475, 2015). "The discrepancy between these results and our findings could be due to differences in downstream signaling activated by EGF in normal versus tumor tissues." (PMID 25595899, 2015). "In addition, we also found that induction of COX-2 and fibronectin by EGF enhanced the interaction between tumor cells and endothelial cells." (PMID 25595899, 2015). "ADAM9 is also known to cleave EGF to promote tumour growth and facilitate angiogenesis." (PMID 25980435, 2015). "To test the possibility that the metastatic process enhanced by EGF-induced PTX3 also occurs by regulating the interaction between tumor and endothelial cells, we examined whether EGF induces the binding of HNSCC cells to HMEC-1 endothelial cells." (PMID 25797258, 2015). "To determine whether induction of COX-2 mediates EGF-induced tumor metastasis, we performed Transwell migration, invasion and transendothelial invasion assays." (PMID 25595899, 2015). "We then interrogated the EAM as to the behaviour of EGFR ubiquitination and phosphorylation over a range of receptor levels spanning from physiological levels (<105 EGFRs per cell) to the pathological levels detected in human tumours (>106 EGFRs per cell), at different EGF concentrations." (PMID 26264748, 2015). "For these reasons targeting EGF and its direct activators could be a valuable alternative to inhibit tumor progression." (PMID 26682280, 2015). "The hypothesis of the present study is that extracellular galectin-3 may promote sphere formation in coordination with EGF or bFGF signaling in tumor sphere medium containing EGF or bFGF." (PMID 25669973, 2015). "Taken together, it is possible that local EGF-rich niche promoted SMG tumor growth." (PMID 26289340, 2015). "Taken together, these observations indicate that the cellular pathways leading to cell proliferation by NT and EGF are more complex in some cancer cell lines and that the ways to develop tools to decrease tumor growth remain more complicated than expected from previous studies." (PMID 26215716, 2015). "The change in basal phosphorylation status and reduced responsiveness in the 3D cultures may be linked to the change in cell proliferative response to EGF and HGF in the tumor spheroids." (PMID 24638075, 2014).